ALOX5 (arachidonate 5-lipoxygenase)
Diseases named in the same sentence as ALOX5 in open-access papers (continued):
Sharing a sentence is not in itself a finding about the gene and the disease.
prostate carcinoma (32 papers, 2008 to 2024). A carcinoma that arises from epithelial cells of the prostate gland. "This counteraction between ALOX15B and ALOX5 indicates an essential switch between pro- and anti-inflammatory precursors, as evidenced in studies of cystic fibrosis macrophages and prostate cancer cells." (PMID 38612771, 2024). "In enzalutamide-resistant prostate cancer cells, the inhibition of ALOX5 interferes with c-Myc signaling, killing cells by enhancing caspase-mediated apoptosis." (PMID 38612771, 2024). "While ALOX5 inhibition triggers marked apoptosis in human prostate cancer cells, it is overexpressed in prostate adenocarcinoma, PDAC, hepatocellular carcinoma, and high-grade astrocytomas." (PMID 38612771, 2024). "According to Ghosh and Myers, the inhibition of ALOX-5 would block the production of its metabolites (leukotrienes), thus triggering apoptosis in prostate cancer cell lines." (PMID 37050202, 2023). "Additionally, overexpression of ALOX5 with its related downstream metabolites has been reported in other cancers such as breast, esophageal, pancreatic, and prostate cancers by stimulation of cell proliferation, tumor angiogenesis, and survival." (PMID 35928873, 2022). "ALOX5 and ALOX15 which convert DHA to resolvin Ds (RvDs) were highly expressed in prostate cancer." (PMID 32469149, 2020).
colorectal cancer (20 papers, 2011 to 2025). A primary or metastatic malignant neoplasm that affects the colon or rectum. "This study found that a haplotype including ALOX5 rs6413416 andrs4986832 was associated with decreased colorectal cancer risk in Caucasians." (PMID 35928873, 2022). "It has also been reported that high ALOX5 expression is significantly associated with a poor prognosis in colorectal cancer, gastric cancer, clear cell renal cell carcinoma, papillary thyroid carcinoma, and other tumors." (PMID 35033072, 2022). "Targeting ALOX5 promotes colorectal cancer cell proliferation, and silencing of ALOX5 inhibited colorectal cancer cell growth." (PMID 33506057, 2021). "In contrast, increased ALOX5 expression has been reported in colorectal cancer cells." (PMID 35928873, 2022). "ALOX5 enhances colorectal cancer cell growth while EGR1 promotes colorectal cancer." (PMID 35155565, 2021). "To confirm whether LXA4-synthesizing enzymes are dysregulated in colorectal cancer, we detected the expressions of ALOX5, ALOX12, ALOX15 and ALOX15B in colorectal cancer tissue." (PMID 31528237, 2019). "However, LXA4-synthesizing ALOX5 was strikingly up-regulated in colorectal cancer." (PMID 31528237, 2019). "In fact, the highest ALOX5 gene correlate observed was with RP11-67C2.2 (r = 0.78), a novel discovery in colorectal cancer." (PMID 37190308, 2023). "In the current study, we examined the expression of COX1, COX2, ALOX5, ALOX5AP and related genes in surgical specimens of colorectal cancer ascertained from The Cancer Genome Atlas (TCGA)." (PMID 37190308, 2023). "Tumor-promoting genes highly correlated with the expression of COX1, COX2, ALOX5 and ALOX5AP are known to increase mitogenesis, mutagenesis, angiogenesis, cell survival, immunosuppression and metastasis in the inflammogenesis of colorectal cancer." (PMID 37190308, 2023). "Our results confirm that COX1, COX2, ALOX5 and ALOX5AP, rate-limiting enzymes of prostaglandin and leukotriene biosynthesis, are all constitutively expressed in colorectal cancer." (PMID 37190308, 2023). "For example, the arachidonate-5 lipoxygenase (ALOX5) and 12-lipoxygenase (ALOX12) played pro-carcinogenic roles in colorectal cancer." (PMID 35928873, 2022). "We examined the expression of major inflammatory genes, cyclooxygenase-1, 2 (COX1, COX2), arachidonate-5-lipoxygenase (ALOX5), and arachidonate-5-lipoxygenase activating protein (ALOX5AP) among 469 tumor specimens of colorectal cancer in The Cancer Genome Atlas (TCGA)." (PMID 37190308, 2023). "Here, we indeed found that ALOX5 activation contributed to enhanced LTB4 but not LXA4 biosynthesis in colorectal cancer." (PMID 31528237, 2019). "It have been found that miR-216a-3p was significantly reduced in pancreatic ductal adenocarcinoma and could affect colorectal cancer cell proliferation by inhibiting COX-2 and ALOX5 expression." (PMID 29440731, 2018). "Thus, ALOX5 activation and LTB4 increase may represent important priming factors in prompting colorectal cancer development." (PMID 31528237, 2019). "As a result, ALOX5 and ALOX12 were strikingly up-regulated in colorectal polyp, compared with those in colorectal cancer surrounding tissue, while there were no significant change in the expressions of ALOX15 and ALOX15B." (PMID 31528237, 2019).
Alzheimer disease (18 papers, 2010 to 2025). A progressive, neurodegenerative disease characterized by loss of function and death of nerve cells in several areas of the brain leading to loss of cognitive function such as memory and language. "ALOX5 serves as a rate-limiting enzyme responsible for the biosynthesis of LTs which are the major mediators of inflammation, finally causing multiple human diseases including asthma, cancers, atherosclerosis, diabetes, and Alzheimer's disease." (PMID 31871543, 2019). "Here, Alox5 (the gene encoding 5-Lox) and Alox5AP (the gene encoding FLAP) expression is predominantly expressed in microglia, in particular in Alzheimer’s disease brains." (PMID 37600518, 2023). "The direct evidence showing a crucial role of ALOX5 in disease arises from the fact that ALOX5 overexpression aggravates memory deficits in a mouse model of Alzheimer's disease." (PMID 31871543, 2019). "Additionally, research has shown that ALOX5 is related to memory deficits and synaptic dysfunction in a mouse model of Alzheimer’s disease." (PMID 36358993, 2022). "ALOX5 is also related to the progression of neurodegenerative diseases such as Alzheimer’s disease." (PMID 36358993, 2022).
glioma (18 papers, 2014 to 2025). A benign or malignant brain and spinal cord tumor that arises from glial cells (astrocytes, oligodendrocytes, ependymal cells). "In contrast, within the context of glioma, ALOX5 has been shown to facilitate disease progression by promoting 5-HETE-mediated immunosuppressive M2 polarization and elevating PD-L1 expression in glioma-associated microglia/macrophages." (PMID 41030501, 2025). "ALOX5 is generally downregulated in NSCLC, and its overexpression has been reported to be associated with tumor progression in gliomas." (PMID 38674080, 2024). "Nordy triggered a differentiation program on glioma stem-like cells (GSLCs) towards an astrocytic phenotype that reduced the frequency of GSCs, and inhibited the growth of xenografted glioma cells by inhibiting the activity of Alox-5." (PMID 24454929, 2014). "In GBM tumors, there is elevated expression of 5-LOX/ALOX5 and FLAP/ALOX5AP relative to healthy brain tissue, which is similar to lower grade gliomas." (PMID 36765904, 2023). "The Macro index comprised of PIK3R5, PIK3R6, ALOX5, ALOX5AP, and ALOX15B serves as a valid prognostic biomarker for gliomas, especially LGG." (PMID 36159811, 2022). "This indicates that the elevated expressions of 5-LOX/ALOX5 and FLAP/ALOX5AP may be glioma-specific." (PMID 36765904, 2023).
leukemia (18 papers, 2011 to 2025). A malignant (clonal) hematologic disorder, involving hematopoietic stem cells and characterized by the presence of primitive or atypical myeloid or lymphoid cells in the bone marrow and the blood. "Recently it was shown that the loss of ALOX5 gene impaired leukemia stem cells and prevented chronic myeloid leukemia in mice." (PMID 21720561, 2011). "It was reported that a loss of the ALOX5 gene prevents the outbreak of leukemia in a mouse model." (PMID 39877387, 2024). "ALOX5 has previously been linked to leukemia stem cells and cancer-related signaling pathways." (PMID 21720561, 2011). "A previous study demonstrated that Alox5 is essential for the maintenance and leukemogenic potential of leukemia stem cells in chronic myeloid leukemia." (PMID 41184226, 2025). "The ALOX5 gene is a common DEG used to compare different growth stages of Haiyang Yellow Chickens, and the ALOX5 gene is reported to play an important role in the proliferation and differentiation of leukemia stem cells." (PMID 37372393, 2023). "In particular, ALOX5 has attracted increasing attention as a key gene for drug targeting and overcoming drug resistance in patients with leukemia." (PMID 30071629, 2018). "Both wildtype and Alox5-/- cells were also able to induce secondary and tertiary leukemias in further rounds of transplantations to new recipient mice (data not shown)." (PMID 24130502, 2013). "In contrast, both wildtype and Alox5-/- cells expressing RE9a induced leukemia in recipient mice, with a median latency of approximately 30 weeks." (PMID 24130502, 2013). "ALOX5 is a promising molecular target for the treatment of CML, as it has been demonstrated that a small molecule inhibitor of ALOX5 significantly delays leukemia onset in mice." (PMID 24130502, 2013). "In contrast, the LSK− population is reduced in CML mice, and depletion of leukemia stem cells (LSCs; BCR-ABL-expressing HSCs) by deleting Alox5 or by inhibiting heat shock protein 90 causes an increase in this LSK− population." (PMID 22675576, 2012). "Apart from tumor bulk cells, ALOX5 is also a critical regulator for leukemia stem cells." (PMID 34121352, 2021). "Therefore, it is highly likely that the PRC2 complex mediates the transcriptional repression of ALOX5 in MLL-rearranged leukemia." (PMID 28500307, 2017). "In a CML model, BCR-ABL-expressing Alox5-/- leukemia stem cells (LSCs) display an increased apoptotic rate as compared to wildtype LSCs, indicating the potential importance of the stem cell population for Alox5 and leukemia development." (PMID 24130502, 2013). "In addition, it is also possible that ALOX5 is required more by RE than RE9a in leukemia development, especially given that RE more strongly upregulates KLF6 expression." (PMID 24130502, 2013). "In addition, ALOX5 has previously been shown to function in both normal hematopoiesis and leukemia development." (PMID 24130502, 2013). "Thus, it would be interesting, whether alterations in the GC box of ALOX5 is of relevance in the context of leukemias carrying MLL-containing fusion proteins such as MLL-AF4." (PMID 39877387, 2024). "Two different studies from the same group have recently shown the relevance of arachidonate 5-lipoxygenase (Alox5) and arachidonate 15-lipoxygenase (Alox15) genes for the survival of CML leukaemia stem cells (LSC)." (PMID 29940987, 2018). "We identified differential methylation of genes that have been related to cancers such as lymphoma (WNT6, TP73, and CD37), leukaemia (MEIS1, HOXA4, and HOXA5) or neuroblastoma (TP73), as well as genes related to cardiovascular diseases (UCN, PRDM16, TCAP, ALOX5)." (PMID 35354948, 2022). "ALOX5 is required for CML development due to the depletion of leukemia stem cells in the absence of Alox5 expression." (PMID 24130502, 2013). "As expected, neither wildtype nor Alox5-/- cells transduced with MigR1 induced leukemia." (PMID 24130502, 2013).
leukemia (continued). "However, Alox5 is not essential for the induction of leukemia by RUNX1-ETO9a in vivo." (PMID 24130502, 2013). "However, as this does not translate to a delay in leukemia onset in vivo, targeting ALOX5 alone is likely insufficient to generate therapeutic benefit, although its inhibition in combination with other treatments may show efficacy and this remains to be examined." (PMID 24130502, 2013).
lung carcinoma (17 papers, 2008 to 2026). "It is plausible that promoter methylation is responsible for reducing both LKB1 and ALOX5 levels in the lung cancer tumour microenvironment, although further work is needed to confirm this." (PMID 34203378, 2021). "Our findings raise further doubts about pharmacological strategies that inhibit 5-LO activity for the treatment of lung cancer, as ALOX5 expression is already significantly reduced in lung tumours." (PMID 34203378, 2021). "ALOX5 is considered to be a candidate biomarker for noninvasive molecular diagnosis of lung cancer." (PMID 35190747, 2022). "This concept is supported by the finding that ALOX5/5-LO appears to have a tumour suppressive role in lung cancer, as global genetic deletion of ALOX5 resulted in substantially increased lung tumour growth in a mouse model where Lewis lung carcinoma cells were implanted directly into the lungs." (PMID 34203378, 2021). "However, deletion of ALOX5 in TME promotes lung cancer progression and metastasis by decreasing T cell number." (PMID 33101283, 2020). "Blocking PARP-1 significantly reduces the levels of ALOX5 and MMP-9 and inhibits neutrophil-mediated lung cancer cell invasion and tumor growth in vivo." (PMID 41155938, 2025). "ALOX5 polymorphisms in non-smokers may increase risk of lung cancer." (PMID 35866375, 2022). "Compared with normal lung tissues, the expression of MMP3, MMP9, and PPARG was increased in lung cancer tissues, and the expression of ALOX5 and ICAM1 was decreased in lung cancer tissues, which was basically consistent with the analysis results in the GEPIA database." (PMID 39440769, 2025).
COVID-19 (16 papers, 2021 to 2025). A disease caused by infection with severe acute respiratory syndrome coronavirus 2. "By mining a published single-cell RNA sequencing dataset in PBMCs from severe COVID-19 patients, the authors found increased ALOX5 expression in CD14+ and CD16+ monocytes and in neutrophils reflecting emergency granulopoiesis." (PMID 34366882, 2021). "Furthermore, the activity of the arachidonate 5-lipoxygenase (ALOX5), a key enzyme in the production of arachidonic-derived mediators exhibits increased expression in obese individuals and severe COVID-19 patients." (PMID 34192269, 2021). "Notably, Schwarz and colleagues reported an upregulation of ALOX5 expression in COVID-19 patients when compared with severe disease." (PMID 34437568, 2021). "Increased expression of ALOX5AP, ALOX5, and plasma LTB4 are also noted in diabetic COVID-19 cases requiring intensive care." (PMID 36143338, 2022). "Congruently, increased ALOX5 activity and ALOX5AP expression are observed in bronchoalveolar lavage (BAL) neutrophils in critical COVID-19 patients." (PMID 36143338, 2022). "We also found an overall increase in ALOX5-ALOX15 interaction products, including RvD1 and RvD2, and an increase in the ALOX5 products 5S, 12S-diHETE, and LTE4 in post-COVID-19 volunteers when compared with healthy volunteers (Figure IIA in the Data Supplement)." (PMID 34238021, 2021). "Regarding the lipoxygenase biosynthetic pathway, we did not detect changes in the levels of ALOX5 or 12 between the different severity groups, unlike ALOX15, which was repressed in all COVID-19 patients, regardless of their severity." (PMID 39916956, 2024).
diabetes (16 papers, 2008 to 2025). "Recently, the ALOX5 polymorphism rs4987105 was identified to confer susceptibility to type 2 diabetes mellitus (T2DM), implicating its role in regulating glucose homeostasis." (PMID 32093765, 2020). "It has been stated that localized increase in ALOX5 has the potential to cause the acute plaque disruption that precedes the onset of symptoms in both the coronary and cerebral circulations in diabetes." (PMID 27781209, 2016). "Among the perturbations correlated with HNF1A overexpression is ALOX5 overexpression, which also impacts beta cell function in diabetes via increased insulin resistance." (PMID 40504147, 2025). "In diabetes, the tubulointerstitium and glomeruli of kidney tissue demonstrated upregulation of ALOX5 and ALOX5AP, and mostly downregulation of COX genes." (PMID 39062733, 2024). "When only Group A and Group B were considered, the differences in the expressions of ALOX5, LTB4R, DDOST, and SIRT1 mRNAs were maintained after adjustment for sex, age, diabetes duration, and use of ACEI, ARB, and statin (P < 0.0001 for all genes)." (PMID 32273829, 2020). "ALOX5 and ALOX15 are major contributions to the generation of lipid peroxides; thus, their overexpression is related to diseases such as systemic sclerosis, certain types of cancers, and diabetes, moreover affecting inflammation and promoting lipid peroxides formation." (PMID 37569384, 2023).
Obesity (15 papers, 2013 to 2024). Accumulation of substantial excess body fat. "A previous study has associated the 5LO gene (also called Alox5) as a candidate gene for obesity and low bone mass when 5LOKO (in the C57Bl/6 background) is subjected under long-term treatment with high fat diet (containing 45% fat by kcal and 3.0g of AA)." (PMID 32849277, 2020). "There is current information on the genetic modulation of ALOX5 and ALOX15 expression during obesity, where ALOX5 promotes leukotrienes, lipoxins, and resolvins production." (PMID 38024342, 2023). "The mRNA expression of a cytochrome P450 gene CYP1B1, ALOX5 (which encodes 5-LOX), and PTGS1 (which encodes COX-1) was upregulated in individuals living with obesity." (PMID 35247847, 2022). "The common targets of obesity, T2DM, and AS are estrogen receptor 2 (ESR2), androgen receptor (AR), CYP19A1, NR3C1, SRC, and arachidonate 5-lipoxygenase (ALOX5)." (PMID 39575382, 2024). "The mRNA expression of CYP1B1, ALOX5 and PTGS1 were upregulated in individuals with obesity." (PMID 38024342, 2023). "Obesity and some tumors activate COX2 and ALOX5 and induce inflammatory responses." (PMID 35448519, 2022). "Gene expression of key enzymes involved in eicosanoid production was reduced (COX1, HPGDS, LPGDS, ALOX15, all p ≤ 0.05) or unaltered (COX2, ALOX5) during critical illness, irrespective of obesity." (PMID 28303483, 2017).